TFRC (transferrin receptor)
Diseases named in the same sentence as TFRC in open-access papers (continued):
Sharing a sentence is not in itself a finding about the gene and the disease.
tumor (continued). "Through transferrin modification, Tf-PE-MEs accumulated at the tumor site efficiently with overexpressed transferrin receptor (TfR) on the surface of A549 cells." (PMID 41303330, 2025). "Nude mice were inoculated with xenogeneic OS cells to study the influence of TFRC knockdown on tumor growth in vivo." (PMID 40510157, 2025). "This mechanistic divergence underscores two tumor-type-specific functions of TRIB2: regulation of iron metabolism through TFRC degradation in HCC, and control of redox homeostasis via the KEAP1-NRF2 pathway in HB." (PMID 41462308, 2025). "TFRC (Transferrin Receptor) is essential for iron uptake and is highly expressed in rapidly proliferating tumor cells." (PMID 40496862, 2025). "The adaptation of tumor cells to increased iron requirements occurs through the overexpression of iron handling-related proteins such as transferrin receptor 1 (TFR1), metal transporter DMT1, and neutrophil gelatinase-associated lipocalin (NGAL)." (PMID 40286136, 2025). "Recent research has highlighted the roles of CD24 and the transferrin receptor 1 (TFR1) in facilitating tumor immune escape, as well as the importance of iron homeostasis in cancer development, particularly in HCC." (PMID 41551164, 2025). "By modifying the outer surface of the nanocages with tumor-specific ligands or peptides, researchers have enhanced their affinity for cancer cell receptors such as transferrin receptor 1 (TfR1)." (PMID 40343307, 2025). "By using an antibody fragment against the human transferrin receptor, immunoliposomes have been effectively utilized in vivo to carry tumor‐suppressing genes into the tumor site." (PMID 40243372, 2025). "The study assessed tumor characteristics and treatment response by measuring Transferrin Receptor (TfR), a key protein for iron uptake, and Ki-67, a marker for cell proliferation." (PMID 40427237, 2025). "Oral PTPN2 inhibitor ABBV‐CLS‐484 disrupts mitochondrial renewal and blocks TFRC‐mediated mitophagy to exert anti‐tumor activities, supporting clinical development for ALK+ ALCL." (PMID 40734623, 2025). "Further examination of the IHC signals in the tumour and stroma between CP‐i and CP‐s revealed that TFRC and PDLIM3 displayed significantly increased abundance in CP‐s, but not in CP‐i, and ALDH5A1 and APM showed no significant changes between CP‐i and CP‐s." (PMID 40697100, 2025). "Common targets employed in cancer therapy are enzyme and receptors overexpressed in tumour cells such as transferrin receptor (TfR), human epidermal growth factor receptor-2, folic acid receptor (FaR), and CD44 receptor." (PMID 40076371, 2025). "The encapsulation and delivery of natural product via apoferritin protein nanocarriers would potentially enhance activity and tumour selectivity through passive (enhanced permeation and retention) and active (transferrin receptor-1) targeting." (PMID 38893527, 2024). "In tumors, 67Ga-citrate administered into the veins binds to transferrin in the serum to form a transferrin-67Ga complex, which acts on the transferrin receptor of the tumor cells and is taken up into the cells." (PMID 39009630, 2024). "In this sense, the transferrin receptor is overexpressed in some types of tumors, including colon, pancreatic, and lung cancers, making them potential candidates for tumor cell targeting with mNPs functionalized with transferrin." (PMID 38791253, 2024). "Among the receptors used for active tumor targeting via receptor-mediated transcytosis, integrins and the transferrin receptor stand out." (PMID 38791253, 2024). "When ferritin binds to the transferrin receptor, it is taken up by tumor tissues, making it an effective vehicle for drug delivery." (PMID 38389925, 2024). "Previous studies have demonstrated that tumor cells often upregulate transferrin receptor 1 (TFR1) while downregulating ferroportin (FNP), thereby limiting iron release." (PMID 39654899, 2024).
tumor (continued). "The observation of TFRC overexpression in certain tumor cells and the inhibitory effect of TFRC deletion on erastin-induced ferroptosis have been documented." (PMID 39210442, 2024). "We observed a significant elevation of CXCL14 expression in tumour cells following TFRC knockdown, a result that aligns with the increased expression observed after anlotinib administration (p‐value < 0.05)." (PMID 39095323, 2024). "Compared with the PDOTs from patients with low TFRC expression, those from patients with high TFRC expression exhibited weaker tumour‐killing effects following anti‐PD‐1 antibody treatment (p < 0.05)." (PMID 39095323, 2024). "Immunohistochemical analyses of mouse tumours with TFRC knockdown revealed that both CXCL14 expression and the CD8+ T‐cell counts were significantly increased in the shTFRC group compared with the control group." (PMID 39095323, 2024). "The hypoxic environment of HCC drives tumor cells to outcompete macrophages for iron by upregulating the transferrin receptor (TFRC), the primary receptor for transferrin-mediated iron uptake, leading to M2-like TAM polarization in vitro." (PMID 39610917, 2024). "The expression levels of TFRC in pan-carcer were also analyzed, and the box plot demonstrated differential expression of TFRC between normal and tumor tissue samples across multiple tumors." (PMID 38336764, 2024). "These NPs were derived from ferritin, a protein that naturally forms a cage-like structure suitable for surface functionalization/drug loading and binds transferrin receptor 1 (TfR1) overexpressed on tumor cells, to facilitate tumor-targeted delivery." (PMID 39339217, 2024). "The hypoxic HCC microenvironment prompts tumor cells to compete with macrophages for iron through increased transferrin receptor (TFRC) expression, the primary receptor for transferrin‐mediated iron uptake." (PMID 38297372, 2024). "IH detection showed that circ-TFRC downregulation suppressed Ki67 expression in tumor tissues, suggesting that circ-TFRC downregulation inhibited OC cell proliferation." (PMID 38678242, 2024). "To further investigate the role of CXCL14, we assessed CXCL14 mRNA and protein expression in tumour cells, as well as protein concentrations in the culture supernatants, following TFRC silencing in HepG2 and PLC/PRF/5 cells." (PMID 39095323, 2024). "Targeted ligand modification decorates nanodrug surfaces with specific ligands that bind to receptors overexpressed on tumor cells, such as transferrin receptor (TfR), folate receptor (FR), and epidermal growth factor receptor (EGFR)." (PMID 39834835, 2024). "Moreover, the association of low TFRC expression in tumour specimens with enhanced responsiveness to anti‐PD‐1‐based immunotherapy suggests that TFRC levels could serve as a biomarker for predicting the treatment efficacy of anti‐PD‐1‐based approaches in HCC patients." (PMID 39095323, 2024). "The transferrin receptor (TfR) is highly expressed in numerous tumor cells including HCC cells due to abnormal iron metabolism." (PMID 39339402, 2024). "The patients with low TFRC expression in their resected tumour specimens exhibited a stronger response to anti‐PD‐1‐based treatment (30% vs. 9.09%, p < 0.01)." (PMID 39095323, 2024). "Consistent with our study, TFRC links iron metabolism and immunity, which together influence the tumor immune microenvironment." (PMID 38602575, 2024). "Mechanistically, LASS2 interacts directly with TFRC to regulate iron homeostasis in these tumour cells." (PMID 38419028, 2024). "Cyanin5.5-labeled hHFt-DOX, specifically bound and subsequently entered HT29 tumor cells (colon adenocarcinoma) via interaction with overexpressed transferrin receptor 1, released DOX into the lysosomes." (PMID 39274893, 2024). "Due to the vital role of ferroptosis in tumorigenesis, our comprehension of the mechanisms governing tumor advancement and prognosis in TFRC has notably progressed." (PMID 39131609, 2024).
tumor (continued). "In hypoxic TME, upregulation of transferrin receptor 1 (TfR1) in humans or T cell immunoglobulin mucin receptor 2 (TIM-2) in mice enhances the uptake of NP-loaded drugs by tumor cells." (PMID 38911968, 2024). "We developed a mouse tumour model with TFRC knockdown utilizing a lentiviral vector to transduce short hairpin RNA (shRNA) targeting the TFRC gene into the Hepa1‐6 cell line." (PMID 39095323, 2024). "Targeted delivery and imaging exploit the ability of heavy chain ferritin (H ferritin) to bind the transferrin receptor CD71, which is overexpressed in metabolically active iron‐demanding cells including tumor cells." (PMID 39541599, 2024). "The patients with low TFRC expression showed high expression of CXCL14 and harboured significantly more CD8+ T cells in tumour tissues compared with the patients with high TFRC expression (all p‐values < 0.05)." (PMID 39095323, 2024). "Studies indicate that tumor cells competitively inhibit transferrin receptor 1 (TFR1), limiting iron supply and modulating macrophage energy metabolism, promoting M2 polarization while decreasing their sensitivity to ferroptosis." (PMID 39575419, 2024). "In GBM, metabolic reprogramming in the tumour microenvironment leads to high expression of TFRC, which provides more iron for tumour progression and drives tumour progression." (PMID 38685674, 2024). "To gain insight into how TFRC‐mediated iron reduction affects human colon tumorigenesis, we treated patient‐derived tumor colonoids with iron chelator deferoxamine (DFO) and performed an RNA‐seq analysis." (PMID 36703617, 2023). "We observed an elevated level of one protein, Transferrin receptor protein 1 (TfR1), in proximally located tumours versus in distally located tumours (proximal mean = 1.66, distal mean = 0.21, p = 4.21 × 10–8)." (PMID 37596405, 2023). "Sgt-94 is an anti-transferrin receptor antibody-engineered liposome encapsulated with a Rb94 plasmid DNA, representing a clinical perspective in phase I in patients with neoplasm (NCT01517464)." (PMID 36964609, 2023). "TFRC‐mediated iron uptake is at the center of this feed‐forward loop, which facilitates tumor cell survival in CRC." (PMID 36703617, 2023). "KLF14 exerts its anti-tumor function by inhibiting Iron-responsive element-binding protein 2 (IRP2), which then causes transferrin receptor-1(TfR1) downregulation and ferritin upregulation on the basis of IRP-IREs system." (PMID 36600258, 2023). "The tumor numbers at sizes of 1–2 and 2–3 mm were also reduced by TFRC depletion in mice treated with a high iron diet." (PMID 36703617, 2023). "Univariate analyses showed that TFRC expression, NIH risk degree, mitotic figures, and tumor size were significantly correlated with OS and RFS." (PMID 37675227, 2023). "Four proteins implied that three proteins of Mo-Mac cells were activated post-treatment, but the TFRC of the tumor cells decreased." (PMID 37760429, 2023). "Although the transferrin receptor (Tf-R) is widely distributed in the body, its expression on the surface of tumor cells is significantly enhanced." (PMID 38067497, 2023). "Here, we found that increased TFRC expression was closely related to tumor relapse and poor prognosis, which suggested that TFRC has a role in carcinogenesis." (PMID 37675227, 2023). "Transferrin receptor (TfR) is overexpressed on a variety of metastatic and drug-resistant tumor cells (including brain cells)." (PMID 37919282, 2023). "A single protein, Transferrin receptor protein 1 (TfR1), was elevated in patents with proximally sided tumours versus patients with distally sided tumours." (PMID 37596405, 2023). "Like iron chelation and TFRC disruption, POLD1 reduction caused increased DNA replication stress, DNA damage response (DDR), apoptosis and repressed tumor growth." (PMID 36703617, 2023). "We found that TFRC depletion significantly decreased total tumor number and tumor burden under both diets." (PMID 36703617, 2023).
tumor (continued). "Tumor cells have a dysregulated iron metabolism and overexpress the transferrin receptor on their surface to increase the cellular uptake of iron." (PMID 36900329, 2023). "In mammals, extracellular ferritin (nanocages) that are self-assembled by 24 subunits can be found in serum in a secreted form, and HFn can be effectively delivered to tumor cells through TFRC-mediated endocytosis." (PMID 37041636, 2023). "IHC analysis of mouse tumor samples showed that the expressions of TFRC and Ki-67 were downregulated in the tumor tissues of mice with knockdown of TFRC." (PMID 37644594, 2023). "Targeted delivery mediated by transferrin receptor produces the greatest tumor suppressor effect in vivo." (PMID 37919282, 2023). "Tf can specifically bind to the transferrin receptor (TfR), which is highly expressed on the surface of tumor cells." (PMID 36768966, 2023). "By immunohistochemical staining of 32 pairs of tumor and para-cancer tissues from our hospital, we found that the expression levels of TFRC (P < 0.0001) and SLC7A11 (P < 0.0001) in tumor tissues were significantly higher than those in para-cancer tissues." (PMID 37940859, 2023). "The findings showed that AHNAK, POLE2, SHMT2, NR2F1, and TFRC expression in tumor tissues was substantially higher than in normal tissues (P < 0.05)." (PMID 38103068, 2023). "The transferrin receptor (TfR) is another target for tumor-targeted delivery of liposomes using antibodies, of which OX26 mAb is the most representative ligand." (PMID 36678845, 2023). "Tumor cells with higher expression of TFRC had a better therapeutic effect when treated with selumetinib and cobimetinib, but had stronger resistance against everolimus, dasatinib, erlotinib, and lenvatinib." (PMID 37940859, 2023). "For example, the up-regulation of the Transferrin Receptor 1 (TfR1) (responsible for cellular iron intake) and ferritin (the cellular iron storage protein) by malignant cells seems to be essential for tumor progression." (PMID 37273145, 2023). "Studies have shown that human heavy chain ferritin (HFn) can specifically target the transferrin receptor 1 (TfR1) overexpressed by tumor cells." (PMID 36999977, 2023). "To further characterize the effect of TFRC on tumor prognosis, we performed univariate and multivariate analyses using the Cox-proportional hazards model." (PMID 36483569, 2022). "As a natural tumor target, H-Ferritin is mediated by transferrin receptor-1 (TfR1) and is expected to target the cell nucleus." (PMID 36015275, 2022). "In the scL-RB94 nanocomplex, a plasmid DNA encoding human RB94 is encapsulated within a cationic liposome whose surface is decorated with an anti-transferrin receptor (TfR) single-chain antibody fragment (TfRscFv) as a tumor-targeting moiety." (PMID 36291878, 2022). "The expression of TFRC (P < 0.001), age (P < 0.001), grade (P < 0.001), and radiation therapy (P = 0.0119) were highly correlated to tumor prognosis through univariate Cox regression." (PMID 36483569, 2022). "Except for immature erythroid cells, most normal cells have low transferrin receptor (TfR) expression, but actively proliferating tumor cells show high levels of TfR." (PMID 36297527, 2022). "For the tumor microenvironment, the ESTIMATE algorithm identified that TFRC expression was associated with the stromal score (p < 0.01), not with the immune score and tumor purity in LGG." (PMID 36483569, 2022). "We found that iron supplementation increases the anti-tumor effect of VC, which was influenced by the cellular iron uptake pathway–transferrin (TF)/transferrin receptor (TFR) system." (PMID 36139668, 2022). "For example, transferrin (Tf) is treated as a targeting ligand for tumor, or brain targeting due to the overexpress of the transferrin receptor (TfR) in cancer cells and the blood-brain barrier (BBB) endothelial cells." (PMID 36134930, 2022). "Gallium binds transferrin and enters tumor cells via transferrin receptor 1, which results in disruption of iron metabolism." (PMID 35502218, 2022).
tumor (continued). "For example, hepcidin, ferritin, transferrin, and transferrin receptor 1 (TFR1) levels are higher in tumor cells than in normal cells." (PMID 34962017, 2022). "Our study illustrated that the TFRC positively correlates with tumor progress factors, such as IDH mutation status and clinical tumor grade." (PMID 36483569, 2022). "We then used various bioinformatics methods and mathematical models to analyze those data, aiming to investigate the clinical significance of TFRC in LGG and illustrate its association with tumor immunity." (PMID 36483569, 2022). "CLDN7, PRKCB, EEF2 and TFRC protein levels were all found at higher levels in high LN yield tumours (q = 0.0283)." (PMID 35043009, 2022). "The result showed that TFRC was mainly expressed in tumor cells, vascular endothelial cells, and macrophages." (PMID 36483569, 2022). "To explore the biological roles of TFRC in LGG, we performed GSEA to find the gene sets or tumor-associated pathways." (PMID 36483569, 2022). "Transferrin receptor (TFRC) is a protein located on the membrane whose expression correlates with tumor stage or cancer progression." (PMID 36052168, 2022). "Transferrin receptor-mediated ROS promotes ferroptosis of human granulosa-like tumor cells via regulating ACSL4." (PMID 35242038, 2022). "To understand the correlation between TFRC and tumor clinicopathological factors, we conducted a correlation analysis in LGG." (PMID 36483569, 2022). "The transferrin receptor is expressed on some cancers and the transferrin has been chosen as a ligand for tumor-targeted delivery." (PMID 35631507, 2022). "In the same year, we added to the system an antibody against transferrin receptor as a targeting moiety, demonstrating in vitro, using tumor spheroids, that the targeting was improved and transcytosis from endothelial cells to the spheroids occurred." (PMID 33623931, 2021). "At the same time, YTHDF1 and iron-related genes (FTH1 and TFRC) are significantly upregulated in tumor tissues." (PMID 34899345, 2021). "Accumulating evidence has revealed the participation of TFRC in tumor onset and progression, and its overexpression has been proven in many cancers." (PMID 34444760, 2021). "Transferrin receptors (TFR) have been reported to be overexpressed 100-fold more in tumor cells than in normal cells, as iron supplementation is desired to maintain the metabolism, proliferation and survival of tumors." (PMID 34959271, 2021). "These HFn nanocages were demonstrated to display tumor homing due to the specific interaction between the HFn nanocage and transferrin receptor 1, which is overexpressed in most tumor tissues." (PMID 33562574, 2021). "In general, transferrin can be modified to the surface of cationic liposomes via crosslinking or electrostatic adsorption to obtain transferrin-receptor-mediated tumor targeting ability." (PMID 34959271, 2021). "Ferric ammonium citrate (FAC) activates the transferrin receptor (TFRC), increases the iron content, and suppresses the cell viability of the human granulosa-like tumor cell line (KGN)." (PMID 34369274, 2021). "The transferrin receptor (TfR) is a particularly attractive target as it is expressed on many dividing cell-types and has therefore often been chosen for targeting tumour cells." (PMID 34086733, 2021). "TFRC, an indispensable iron transporter for cellular iron absorption, is critical in carcinogenesis and tumor progression and is dysregulated in numerous cancers." (PMID 33989111, 2021). "TfRC expression is correlated with poorer outcomes in several cancers, the overexpression of TfRC provided more irons to meet the metabolic needs of the cancer cells while downregulation of TfRC has inhibited the growth of tumor." (PMID 34012978, 2021). "Considering that MYCN and TFRC are both deregulated in a variety of tumor types, our finding points to a tumor vulnerability that can be therapeutically exploited." (PMID 34011924, 2021).